TGM3 (transglutaminase 3)
Diseases named in the same sentence as TGM3 in open-access papers (continued):
Sharing a sentence is not in itself a finding about the gene and the disease.
cancer (18 papers, 2007 to 2024). A tumor composed of atypical neoplastic, often pleomorphic cells that invade other tissues. "TGM3 is associated with a various type of human cancer, including laryngeal carcinoma, hepatocellular carcinoma, esophageal carcinoma, colorectal cancer, and head and neck cancer (HNC)." (PMID 38589352, 2024). "According to the Human Protein Atlas (HPA) and TIMER databases, we evaluated the protein expression levels of TGM3 in different organs and tissues as well as their association with immune cell infiltration and immunotherapeutic response in pan-cancers." (PMID 36685895, 2022). "In some cancers, the expression level of TGM3 was associated with some clinical stages of cancers with slight statistical significance in KIPAN, KIRC, LIHC, OV, UVM and UCS." (PMID 36685895, 2022). "In the present study, we assessed the patterns of TGM3 mutation in pan-cancer." (PMID 36685895, 2022). "High expression level of TGM3 was detrimental to the survival in most cancer types, except PAAD, which suggested that TGM3 may be a risk prognostic factor in most cancers." (PMID 36685895, 2022). "The present findings suggest that TGM3 may be a highly specific diagnostic and prognostic biomarker in different types of carcinomas, especially in epithelial carcinoma." (PMID 36685895, 2022). "TGM3 encodes an enzyme that is involved in immune regulation of cancer." (PMID 34721525, 2021). "Although TGM3 down-regulation has been found in many cases, the molecular mechanism that causes the silencing of TGM3 expression in most cancers remains unclear." (PMID 24289313, 2013). "However, the molecular mechanisms underlying TGM3 and cancers remain elusive, especially in cSCC." (PMID 38589352, 2024). "Notably, TGM3 expression was significantly associated with OS in several cancer types." (PMID 36685895, 2022). "In addition, whether the TGM3 gene might be a valuable diagnostic or therapeutic biomarker for cancer, especially for HNC, needs to be further investigated." (PMID 24289313, 2013). "In the present study, we showed that TGM3 expression was negatively correlated with B cells, DCs and neutrophil cells in most cancers, including STAD, TGCT, PRAD, LUSC, THYM and HNSC, according to the TIMER database." (PMID 36685895, 2022). "We found a high correlation (p < 0.05) between TGM3 and immune checkpoint gene expression in several cancer types." (PMID 36685895, 2022). "Eight cancer types closely related with TGM3 expression were utilized to evaluate the oncogenic functional annotation and KEGG pathway analysis." (PMID 36685895, 2022). "TGM3, a gene that functions as a tumor suppressor and in repressed in several cancer entities was also deleted and downregulated in EOBRCA." (PMID 36352274, 2022). "We then analyzed the expression of TGM3 in different clinical stages according to the clinical tumor stage classification form TCGA pan-cancer." (PMID 36685895, 2022). "In the present study, CD4+ cells, neutrophils, and DCs were also significantly altered in many cancers with the change of TGM3 expression level." (PMID 36685895, 2022). "The present study aimed to explore the clinical and prognostic function of TGM3 in pan-cancer as well as to explore the relationship of TGM3 expression with clinical stage, survival rate, prognosis condition, immune infiltration and mutation indicators." (PMID 36685895, 2022). "In the present study, we selected eight cancer types, some of which belonging to epithelial neoplasms and others with significant changes in TGM3 expression levels, for analysis." (PMID 36685895, 2022). "We then evaluated the multifaceted prognostic value of TGM3 in cancers with univariate Cox regression analysis." (PMID 36685895, 2022). "Although high TGM3 expression mainly plays a carcinogenic role in most tumor types, the expression level of TGM3 is lower in tumor tissues than normal tissues in some cancers, such as LAML and ALL, and higher TGM3 expression indicates poorer prognosis." (PMID 36685895, 2022).
cancer (continued). "We performed a bioinformatics analysis of TGM3-related bioinformatics data to assess the expression level of TGM3 in different tissues and its correlation with different types of cancers." (PMID 36685895, 2022). "To elucidate the biological and molecular function of TGM3 in various cancer types, we performed GSEA." (PMID 36685895, 2022). "TGM3 is a regulatory protein in many types of cancer and can be used as a carcinoma marker." (PMID 38589352, 2024). "GSEA analysis elucidated the biological and molecular function of TGM3 in various cancer types." (PMID 36685895, 2022). "TGM3 was closely correlated with immune regulator gene expression and had a high correlation (p < 0.05) with chemokine receptors, MHCs, immunoinhibitors, and immunostimulators in various cancer types." (PMID 36685895, 2022). "We separated the cancers into low-TGM3 expression and high-TGM3 expression tumor groups." (PMID 36685895, 2022). "High expression level of TGM3 was also related to higher clinical stages in most cancers." (PMID 36685895, 2022). "Furthermore, in most cancer types, TGM3 was inversely correlated with TMB, MSI, and methylation, suggesting that TGM3 expression can be used to assess potential therapeutic response, especially immune-related targeted therapy." (PMID 36685895, 2022). "GSEA based on KEGG and oncogenic functional annotation, indicated that TGM3 regulated multiple important oncogenic functional modules in tumors, and that TGM3 protein or transcripts was involved in the regulation of potential cancer immunogenicity and immunotherapeutic effects in various cancers." (PMID 36685895, 2022). "Using an online database, we found that TGM3 was differently expressed in numerous cancer types." (PMID 36685895, 2022). "Considering that the expression levels of WNK2, CYP1A1, PAX5, XRCC1, and TGM3 have been reported to be closely related to the development of cancer, we then detected the expression levels of these genes in SK-MES-1 and A549 cells after transfection of circFLNA and miR-486-3p mimic." (PMID 33500536, 2022). "Recently, new data appeared suggesting that TGM3 may play a role in the propagation of cancer by modulating epithelial-to-mesenchymal transition (EMT) in epithelial carcinomas." (PMID 32872587, 2020). "Here, we summarize the main advances that have recently been achieved in TGM3 analyses in skin and hair follicle biology and also in understanding the functional role of TGM3 in human tumor pathology as well as the reliability of its prognostic clinical usage as a cancer diagnosis biomarker." (PMID 32872587, 2020). "TGM3 was shown to be either downregulated or upregulated in various carcinomas." (PMID 32872587, 2020). "Because the data suggested that TGM3 may affect immune cell differentiation, we assessed the relationship between TGM3 expression and the level of infiltrating immune cells in each cancer type from pan-cancer to elucidate how TGM3 regulates the immune microenvironment of tumors." (PMID 36685895, 2022). "However, it remains unknown how TGM3 acts as a cancer-related molecule in the pathogenesis of different tumors." (PMID 36685895, 2022). "The data were consistent with classic tumorigenesis genes and pathways of these cancers, indicating that expression of TGM3 on tumor cells may have be regulated by B cell and T cell activation linker proteins, thereby affecting the immune reaction, and promoting both immune and oncogenic pathways." (PMID 36685895, 2022). "Additionally, TGM3 also influenced methylation modification in some cancer types." (PMID 36685895, 2022). "However, it remains unclear how transglutaminase 3 (TGM3) affects in pan-cancer." (PMID 36685895, 2022). "We first provide evidence that the exogenous expression of TGM3 in HNSCC cell lines inhibits the proliferation, colony formation and induces the apoptosis in cancer cells in vitro and tumorigenicity in vivo." (PMID 24289313, 2013).
cancer (continued). "We first evaluated the expression level of TGM3 in TCGA, TARGET and GTEx databases of pan-cancer." (PMID 36685895, 2022). "For example, several genes from the final part of the ranking, present specific clear information on MCC against the rest skin states as LGR5, POU4F1, SOSTDC1, KRT20, TGM3 and MYO15A genes, as their gene expression levels are opposite against to the other cancer-related skin states." (PMID 29750795, 2018). "However, TGM3, an important paralog of TGM6, has been studied in cancer." (PMID 30884206, 2019). "However, the biological function and molecular mechanism of the TGM3 gene in cancer initiation and progression have not been reported." (PMID 24289313, 2013). "As expected, several of the top 10 up-regulated genes in ND (compared to T) were related to formation of the epidermis (e.g. TGM3 and SCEL) and were not altered in cancer." (PMID 22280838, 2012). "These genes were not included in our original dataset either because they were not in the "Cancer Gene Census" category of COSMIC (MMP2, PIK3C3, TGM3, EPHA3) or because there was no crystal structure available (DCLK3)." (PMID 21575214, 2011). "From a clinical point of view, IL1RN, MAL and TGM3 were not clearly identified as potential HNSCC markers, while few data have been published concerning the implication of FN1, KRT, MMP1, PLAU and SPARC in this type of cancer." (PMID 19835631, 2009).
tumor (18 papers, 2007 to 2026). "Deguelin therapy reversed the accelerated tumor growth, as manifested by tumor weight and tumor volume, caused by TGM3 knockdown in a subcutaneous xenograft tumor model." (PMID 38589352, 2024). "To investigate the molecular mechanisms underlying the tumor-suppressing effect of TGM3, we performed RNA-sequence analysis on control and TGM3-knockdown A431 cells." (PMID 38589352, 2024). "Deguelin, a PI3K-AKT inhibitor therapy reversed the accelerated tumor growth, as manifested by tumor weight and tumor volume, caused by TGM3 knockdown in a subcutaneous xenograft tumor model." (PMID 38589352, 2024). "The TIMER database was then utilized to evaluate the relationship between TGM3 expression and tumor-infiltrating immune cells, which revealed closely association with the immune infiltration of B cells, CD4+ cells, CD8+ cells, neutrophils, macrophages and DCs." (PMID 36685895, 2022). "Several studies made on tumor cell lines indirectly demonstrated that the suppressive effect of the TGM3 protein on cell proliferation was caused by apoptosis and not by the alteration of the cell cycle." (PMID 32872587, 2020). "Our data demonstrated that the reduced expression of TGM3 in HNSCC was associated with poorer pathological tumor differentiation (P = 0.0037), consistent with the findings described in ESCC and OSCC." (PMID 24289313, 2013). "Furthermore, TGM3 deficiency activates PI3K-AKT signaling pathway in subcutaneous A431 xenograft tumor model." (PMID 38589352, 2024). "Therefore, the role of TGM3 gene alteration and mutation as a tumor marker should be further investigated." (PMID 36685895, 2022). "To assess the impact of TGM3 on tumor growth in vivo, we established a subcutaneous xenograft tumor model in NOD/SCID mice." (PMID 38589352, 2024). "Collectively, our findings suggest that TGM3 acts as a tumor suppressor in cSCC both in vitro and in vivo." (PMID 38589352, 2024). "TGM3 exhibited tumor-suppressing activity by regulating cell proliferation, migration, and invasion both in vitro and in vivo." (PMID 38589352, 2024). "The classic EMT phenotypes, including the downregulation of E-cadherin and the upregulation of N-cadherin, were observed in both TGM3-knockdown cSCC cells and the TGM3-knockdown subcutaneous xenograft tumor model." (PMID 38589352, 2024). "The product of the TGM3 gene has been also identified as an important inhibitor of cell proliferation and enhancer of apoptosis considered a significant anti-tumour factor." (PMID 38773369, 2024). "TGM3-overexpression/knockdown cSCC cell lines were utilized to detect TGM3’s impact on epithelial differentiation as well as tumor cell proliferation, migration, and invasion in vitro." (PMID 38589352, 2024). "Loss of TGM3 significantly decreased expression of KRT14 in cSCC cells and subcutaneous xenograft tumor models." (PMID 38589352, 2024). "In this study, we have identified Transglutaminase 3 (TGM3) as a novel cSCC tumor suppressor that regulates the PI3K-AKT axis." (PMID 38589352, 2024). "As a novel cSCC tumor differentiation marker, TGM3 expression was positively correlated with cell differentiation." (PMID 38589352, 2024). "In this study, we discovered a novel cSCC tumor suppressor gene, TGM3, which regulates the PI3K-AKT signaling pathway and the EMT process." (PMID 38589352, 2024). "Taken together, these bioinformatic analyses identified TGM3 as an important biomarker for clinical tumor prognosis and evaluation of treatment efficacy." (PMID 36685895, 2022). "In tumor immunology pathways, TGM3 was negatively correlated with a variety of immune-related pathways, such as NK cell-mediated cytotoxicity, T cell receptors, B cell receptors and toll-like receptor signaling pathways, in CESC, COAD, PRAD and OV." (PMID 36685895, 2022).
tumor (continued). "For example, TGM3 depletion in tumor cell lines Huh7 and 97H led to diminished cell proliferation, increased levels of cleaved caspase 3/apoptosis, and decreased colony formation, thereby contributing to decreased tumorigenesis and invasion." (PMID 32872587, 2020). "TGM-3 expression was cytoplasmic and nuclear staining expressed in keratinized layer, stratum granulosum and stratum spinosum in controls and tumour cells." (PMID 29953521, 2018). "Finally, TGM-3, expressed in tumor tissues and serum, has shown strong prognostic value in the management of OSCC patients undergoing chemotherapy and radiotherapy." (PMID 40818120, 2026). "Additionally, we have found that TGM3 can serve as a biomarker for tumor differentiation to distinguish the malignant potential of tumors." (PMID 38589352, 2024). "Furthermore, TGM3 serves as a novel cSCC tumor differentiation marker through binding to KRT14 and promoting its degradation." (PMID 38589352, 2024). "Deguelin, a PI3K-AKT inhibitor, blocked cSCC tumor growth induced by TGM3 knockdown in vivo." (PMID 38589352, 2024). "Taken together, TGM3 inhibits cSCC tumor growth via PI3K-AKT signaling, which could also serve as a tumor differentiation marker and a potential therapeutic target for cSCC." (PMID 38589352, 2024). "Additionally, subcutaneous xenograft tumor models were employed to examine the effect of TGM3 knockdown on tumor growth in vivo." (PMID 38589352, 2024). "Finally, molecular and biochemical approaches were employed to gain insight into the tumor-suppressing mechanisms of TGM3." (PMID 38589352, 2024). "Deguelin also reversed TGM3 knockdown-induced KRT14 higher expression in xenograft tumor models." (PMID 38589352, 2024). "In this study, we identified TGM3 as a novel cSCC tumor suppressor that acts via the PI3K-AKT axis." (PMID 38589352, 2024). "In addition to its constitutive expression, studies have primarily reported that TGM3 is a tumor-related suppressor in carcinogenesis that is involved in the apoptosis mechanism." (PMID 36685895, 2022). "Finally, the mRNA expression differences of TGM3 among peri-tumor and tumor samples were summarized by integrating statistics from TCGA databases." (PMID 36685895, 2022). "We also investigated whether TGM3 leading to activation or inhibition of this pathway is closely related to tumor heterogeneity." (PMID 36685895, 2022). "The results implicated TGM3 in the regulation of the tumor immune response through negative modulation of immune inhibitory checkpoints, particularly for STES, LUSC, CESC, TGCT and PRAD, but without statistical significance." (PMID 36685895, 2022). "Furthermore, TGM3 silencing caused by DNA hypermethylation in HNSCC promoted cell growth and inhibited apoptosis activities, indicating its potential tumor suppressor role." (PMID 32076707, 2020). "It was illustrated that the immunohistochemical evaluation of TGM3 expression level could help to predict tumor recurrence and contribute to improve the treatment outcome of patients with attentive follow-up." (PMID 32076707, 2020). "After evaluating the anti-tumor activity of TGM3 in vitro, we next analyzed whether exogenous TGM3 expression affected tumorigenicity in vivo using an HN30 xenograft model in BALB/C nude mice." (PMID 24289313, 2013). "The studies prove that TGM3, as a candidate tumor suppressor, contributes to the carcinogenesis and development of HNC and may serve as a useful biomarker for patients with HNC." (PMID 24289313, 2013). "Our results strongly suggest that the TGM3 may be a candidate tumor suppressor and may act as a potential and novel biomarker for HNC." (PMID 24289313, 2013). "RNA-seq analysis showed that PIC upregulated transglutaminase 3 (Tgm3), which was associated with suppression of the phosphoinositide 3-kinase/AKT/mechanistic target of rapamycin pathway, downregulation of proinflammatory and tumor-promoting genes, and enhancement of epithelial repair genes." (PMID 40994154, 2025).
tumor (continued). "Therefore, the detection of TGM3 methylation may shed light on the exploration of potential tumor molecular biomarkers." (PMID 36685895, 2022). "Further analysis of the shared 61 proteins revealed that there were a large number of tumor-related proteins, such as HSPA5, HNRNPH1, HSPA8, TGM3, and SERPINB12." (PMID 37715221, 2023). "Six types of tumor tissues (THCA, HNSC, CESC, PAAD, SKCM and TGCT) were stained with lower TGM3 expression clusters compared with normal tissues." (PMID 36685895, 2022). "The consensus of the classifiers identifies DCLK3, MMP2, TGM3 as oncogenes and PIK3C3 and EPHA3 as tumor suppressors." (PMID 21575214, 2011). "These levels were lower in tumor than in normal samples for KRT4, KRT13, IL1RN, MAL and TGM3 (Wilcoxon test for paired data, p < 0.001)." (PMID 19835631, 2009). "The three top-ranking tumor cohorts of negative correlation were LUSC, PRAD and STAD, which indicated that high TGM3 expression was associated with a potential decreased immune cell infiltration level." (PMID 36685895, 2022). "With 2DE combined with MS platform, transglutaminase 3 (TGM3), heat shock protein 70 (Hsp70), TPM4-ALK fusion oncoprotein 2, myosin light polypeptide 6, keratin I and calreticulin were identified as over-expressed in tumor tissues." (PMID 27053248, 2016). "Exogenous expression of TGM3 in HNC cells could inhibit the proliferation and enhance the apoptosis of HNC cells in vitro and suppress tumor growth in vivo." (PMID 24289313, 2013).
infection (6 papers, 2022 to 2025). The state of being infected such as from the introduction of a foreign agent such as serum, vaccine, antigenic substance or organism. "It is of note that there were six proteins (Chm, Tgm3, Arhgap24, Tanc1, Agap1, Pnkd) that were uniquely expressed on the third day after infection." (PMID 36061859, 2022). "RCAN1, SLC6A6, RHOB, DUSP, TGM3, and TP53INP2 DEGs, which are related to DNA damage-induced apoptosis, autophagy, the cell cycle, and inflammatory repression, were also upregulated after vPdR-36U infection." (PMID 40006915, 2025).
bacterial infection (1 paper, 2023). "In our setting, the P set represents the molecular events related to the potential pathogenicity, lethality, and inflammatory response of the secondary bacterial infection, so TGM3 can be used as the representative mRNA of the P set." (PMID 36838374, 2023).